SHOX2 (SHOX homeobox 2)
Diseases named in the same sentence as SHOX2 in open-access papers (continued):
Sharing a sentence is not in itself a finding about the gene and the disease.
glioma (8 papers, 2015 to 2024). A benign or malignant brain and spinal cord tumor that arises from glial cells (astrocytes, oligodendrocytes, ependymal cells). "The expression levels of SHOX2 were significantly associated with the grades and clinical features of glioma patients, such as IDH status, 1p/19q status, MGMT status and new types." (PMID 37170390, 2023). "Then, the association between SHOX2 expression and somatic mutations was analyzed in the TCGA glioma dataset." (PMID 37170390, 2023). "The results demonstrated that SHOX2 could regulate metabolism and DNA repair associated signaling pathways in glioma." (PMID 37170390, 2023). "Next, U-251MG and LN-229 glioma cell lines were applied to verify the biological functions of SHOX2." (PMID 37170390, 2023). "TCGA database also displayed that SHOX2 mRNA levels in the glioma patients with wild-type IDH were higher compared with patients of IDH-mut and 1p/19q non-codeletion or IDH-mut and 1p/19q codeletion." (PMID 37170390, 2023). "CCK-8, wound healing, Transwell and colony formation experiments showed that SHOX2 knockdown inhibited glioma cell proliferation, migration, invasion and colony formation abilities." (PMID 37170390, 2023). "Then, we analyzed the correlation between SHOX2 expression and TIICs in glioma via ImmuCellAI in TCGA and CGGA databases." (PMID 37170390, 2023). "We analyzed the top 50 genes in glioma via LinkedOmics online database, which were positively or negatively correlated with SHOX2, as shown in the heat map." (PMID 37170390, 2023). "Through in vitro assays, we specifically examined the relationship between SHOX2 mRNA expression and the development and proliferation of gliomas." (PMID 37170390, 2023). "Overall, the analyses showed that high levels of SHOX2 mRNA expression were correlated with a poorer prognosis in pan-cancers, including in glioma (Especially in the LGG)." (PMID 37170390, 2023). "In vitro assays were applied to verify the biological functions of SHOX2 in glioma cells via CCK-8, wound healing, Transwell and colony formation assays." (PMID 37170390, 2023). "A summary of our results suggested that SHOX2 mRNA expression levels were increased in multiple tumors, including glioma." (PMID 37170390, 2023). "In colony formation assay, reduced SHOX2 expression impaired the colony formation capacities of glioma cells." (PMID 37170390, 2023). "The expression of SHOX2 in glioma patients with higher WHO grade is higher in TCGA, CGGA and GSE16011 databases." (PMID 37170390, 2023). "Among them, 22 genes had a degree score ≥10 and 6 genes (WT1, HOXA2, HOXC6, MMP9, SHOX2 and MYOD1) were selected to construct a signature to classify glioma patients into low- or high-risk groups." (PMID 36118887, 2022). "Heatmap analysis showed that WT1, HOXA2, HOXC6, MMP9 and SHOX2 are highly expressed in high-hypoxia glioma tissues in the TCGA, whereas MYOD1 expression is reduced." (PMID 36118887, 2022). "IHC staining of primary and recurrent glioma tissues suggested that the expression of HOXC6, MMP9, MYOD1 and SHOX2 are associated with the degree of hypoxia in gliomas as well in recurrent cases." (PMID 36118887, 2022). "Interesting, in the current study, we found that HOXC6, MMP9 and SHOX2 expression were increased in the glioma tissues with promoter unmethylation of MGMT, while MYOD1 was reduced." (PMID 36118887, 2022). "Knockdown the expression of SHOX2 significantly reduced the TMZ-resistance induced by hypoxia in glioma cells." (PMID 36118887, 2022). "Therefore, while studying the biological functions of SHOX2 in pan-cancers, we further studied the biological function of SHOX2 in glioma." (PMID 37170390, 2023). "SHOX2 knockdown inhibited glioma cell proliferation, migration and colony formation ability." (PMID 37170390, 2023). "Based on these results, it was hypothesized that SHOX2 promoted the growth of pan-cancers, particularly in glioma." (PMID 37170390, 2023).
glioma (continued). "We further verified the relationship between SHOX2 expression and TIICs in glioma via TIMER2." (PMID 37170390, 2023). "The expression level of SHOX2 was related to the grades and clinical features of glioma patients." (PMID 37170390, 2023). "The expression of HOXC6, MMP9, SHOX2 and MYOD1 was associated with hypoxia degree in glioma tissues and in recurrent cases, had a remarkable diagnostic value and a significant relationship with disease free survival in glioma patients." (PMID 36118887, 2022). "Ultimately, we identified six novel hypoxia-driven genes for reliable prognostic prediction in gliomas and found that SHOX2 might be a potential target to overcome the TMZ resistance induced by hypoxia." (PMID 36118887, 2022). "SHOX2 is a key transcriptional regulator in several genetic diseases, and SHOX2 has been shown to be a valuable biomarker in the diagnosis and evaluation of many types of cancers, including gliomas." (PMID 36118887, 2022). "Similarly, we found that the expression of HOXC6, MMP9 and SHOX2 was higher in recurrent glioma tissues compared with primary glioma tissues and the expression of MYOD1 was decreased, while there were no significant changes in WT1 and HOXA2." (PMID 36118887, 2022). "Moreover, through performing ROC analysis, we found that HOXC6, MMP9, SHOX2 and MYOD1 had a high diagnostic value (AUC>0.7) to distinguish primary and recurrent glioma tissues." (PMID 36118887, 2022). "Moreover, SHOX2 was highly expressed in glioma tissues with O-6-methylguanine-DNA methyltransferase (MGMT)-unmethylation and temozolomide (TMZ) resistant glioma cell lines, and associated with MGMT expression." (PMID 36118887, 2022). "GSEA were performed for preliminarily exploring the regulated mechanism of SHOX2 in glioma." (PMID 36118887, 2022). "Hypoxia increased the resistance of glioma cells, and suppression of SHOX2 could abolish the effects of hypoxia." (PMID 36118887, 2022). "In conclusion, these results suggested that SHOX2 may be a promising prognostic marker and a potential factor for predicting sensitivity to immunotherapy in patients with malignant tumors, particularly glioma." (PMID 37170390, 2023). "Furthermore, to further studying the biological functions of SHOX2 in glioma (LGG and GBM)." (PMID 37170390, 2023). "Likewise, another study revealed that SHOX2 could also serve as a potential indicator for tumor treatment with a prognostic value for gliomas." (PMID 36118887, 2022). "Higher expression levels of HOXC6, MMP9 and SHOX2, and lower expression levels of MYOD1 were observed in the glioma tissues with promoter-unmethylation of MGMT in TCGA." (PMID 36118887, 2022). "In the present study, through perform IHC, we found that high expression of HOXC6, MMP9 and SHOX2 and low expression of MYOD1 were observed in recurrent glioma tissues." (PMID 36118887, 2022). "We first determined the expression HOXC6, MMP9, SHOX2 and MYOD1 in glioma tissues with promoter-methylation and promoter-unmethylation of MGMT." (PMID 36118887, 2022). "In conclusion, a risk model constructed by 6 hypoxia-driven genes (WT1, HOXA2, HOXC6, MMP9, SHOX2 and MYOD1) provide valuable clinical utility for the prognostic prediction of glioma patients." (PMID 36118887, 2022). "In the current study, we demonstrated that SHOX2 was increased TMZ-resistance glioma cells, while hypoxia can induced the elevation of SHOX2 in glioma cells." (PMID 36118887, 2022). "Interesting, through multivariate COX regression analysis, we found that HOXC6, MMP9, SHOX2 and MYOD1 can act as independent prognostic factors for glioma." (PMID 36118887, 2022). "SHOX2 expression level was significantly correlated with isocitrate dehydrogenase (IDH), 1p/19q, O6-methylguanine DNA methyltransferase (MGMT) status and new types of glioma patients." (PMID 37170390, 2023). "Then, SHOX2 mRNA expression were analyzed in WHO grades and new types of gliomas." (PMID 37170390, 2023).
glioma (continued). "Furthermore, results analyzed in glioma tissues in the TCGA demonstrated that glioma patients with high expression levels of HOXC6, MMP9 and SHOX2 had lower dis-ease-free survival rates." (PMID 36118887, 2022). "Interestingly, results from glioma tissues in the TCGA also indicated that patients with high expression levels of HOXC6, MY-OD1 and SHOX2, and low expression levels of MYOD1, had a lower disease-free survival rate." (PMID 36118887, 2022). "Zhang obtained mRNA transcription information and clinical data of gliomas from the TCGA database and found that the expression of RAB42, SHOX2, IGFBP2, HIST1H3G, and IGF2BP3 negatively correlated with 5-years OS; also, IGF2BP3 expression significantly positively correlated with glioma grades." (PMID 34721530, 2021). "Importantly, SHOX2 might be a potential target for blocking the stimulative effects of a hypoxic environment and TMZ resistance in glioma progression." (PMID 36118887, 2022). "Moreover, SHOX2 and SH2D4A were highly expressed in glioma cell lines, but the difference was not obvious." (PMID 37091145, 2023).
atrial fibrillation (7 papers, 2015 to 2024). A disorder characterized by an electrocardiographic finding of a supraventricular arrhythmia characterized by the replacement of consistent P waves by rapid oscillations or fibrillatory waves that vary in size, shape and timing and are accompanied by an irregular ventricular response. "Other research found an association of Shox2 loss-of-function mutation with enhanced susceptibility to familial atrial fibrillation (AF)." (PMID 31581653, 2019). "Together, our data demonstrate for the first time coding and non-coding variants in SHOX2 in patients with atrial fibrillation." (PMID 27138930, 2016). "In this study, we investigate SHOX2 as a potential susceptibility gene for atrial fibrillation in a large set of patients with early-onset AF." (PMID 27138930, 2016). "It is noted that ectopic pacemaking activities originated from the myocardial sleeves of the pulmonary vein and systemic venous return, both derived from the Shox2+ pro-pacemaking cells in the venous pole, cause atrial fibrillation." (PMID 26682210, 2015). "Similarly, target sequencing of the SHOX2 region in atrial fibrillation (AF) patients identified an AF-associated SNP within the 3′ UTR." (PMID 33777110, 2021). "Overview of SHOX2 variants identified in AF (atrial fibrillation) and SND (sinus node dysfunction) patients and control databases: 1,000 gnomes project (TGP) and the genome Aggregation Database (gnomAD); only the European Non-Finnish populations were considered." (PMID 31354791, 2019). "To investigate a possible role of SHOX2 in atrial fibrillation (AF), we performed a mutational screen in 378 patients with early-onset AF before the age of 60 years (14–60 years)." (PMID 27138930, 2016). "Intriguingly, coding and non-coding variants in the human SHOX2 locus were recently associated with SAN dysfunction and atrial fibrillation, underscoring the value of human-conserved SAN enhancer characterization for functional disease variant screening." (PMID 39389973, 2024). "Wang's study showed that Pitx2 affects two microRNAs (miR-17–92 and miR-106b-25) and indirectly regulates the expression of Shox2 and TBX3, thus causing sinus node dysfunction and increasing the susceptibility to atrial fibrillation." (PMID 35851424, 2022). "Our current study provides first convincing evidence for a link between SHOX2 and atrial fibrillation in humans." (PMID 27138930, 2016).
colorectal cancer (7 papers, 2014 to 2025). A primary or metastatic malignant neoplasm that affects the colon or rectum. "Septin 9 (SEPT9) and short stature homeobox 2 (SHOX2) methylation in circulating cell-free DNA (ccfDNA) are powerful biomarkers for colorectal cancer (CRC) screening, as well as head and neck squamous cell carcinoma staging and monitoring." (PMID 29610456, 2018). "Correspondingly, SHOX2 methylation levels in adenomas and colorectal carcinomas were significantly higher compared to those in normal control tissues (p < 0.001)." (PMID 27660666, 2016). "SEPT9/SHOX2 methylation assays may help to distinguish colorectal cancer and adenomas from normal and inflammatory colonic tissue, as well as advanced from non-advanced adenomas." (PMID 27660666, 2016).
Arrhythmia (6 papers, 2013 to 2025). Any cardiac rhythm other than the normal sinus rhythm. "To provide an extended SHOX2 gene analysis in patients with distinct arrhythmias, we investigated SHOX2 as a susceptibility gene for SND and AF by screening 98 SND patients and 450 individuals with AF." (PMID 31354791, 2019). "This study associates additional rare variants in the SHOX2 gene implicated in the susceptibility to distinct arrhythmias and allows frequency estimations in the AF cohort (3/990)." (PMID 31354791, 2019). "According to current studies on Shox2, SHOX, and SHOX2, SHOX2 is considered to play a critical role in idiopathic short stature and various types of cardiac arrhythmias." (PMID 34262939, 2021). "The mortalityrate can be mitigated with closely related hypomorphic Shox allelereplacing Shox2, however the arrhythmias persist.Early in embryonic cardiac development, Shox2 isexpressed in the SAN, right venous valve, and dorsalmesenchymal protrusion of the heart." (PMID 40351691, 2025). "In summary, several studies have demonstrated that Shox2 is an important regulator of the cardiac conduction system and that alterations of Shox2 expression can impair electrical properties of the heart resulting in sinus node dysfunction, conduction slowing, or arrhythmias." (PMID 27138930, 2016). "Although the mice survive, they still show arrhythmias, suggesting that SHOX2 haploinsufficiency may lead to arrhythmia in humans." (PMID 23455426, 2013). "Previous studies in mouse and zebrafish have suggested a pivotal role for the transcription factor Shox2 during cardiac development, especially in the pacemaker region and sinoatrial node (SAN) function, suggesting SHOX2 as possible susceptibility gene for cardiac arrhythmias." (PMID 27138930, 2016). "Thus, it will be interesting to see if both SHOX2 and ISL1 are involved in human heart disease, especially arrhythmias." (PMID 23455426, 2013).
gastric cancer (6 papers, 2018 to 2024). A primary or metastatic malignant neoplasm involving the stomach. "Interestingly, one recent study reported that SHOX2 was among the most up-regulated genes following the induction of STAT3 activation in Helicobacter pylori-infected patients with gastric cancer, which suggests that SHOX2 may contribute to the initiation and progression of gastric carcinogenesis." (PMID 34465361, 2021). "IGF2-AS has been reported to play anti-cancer efficacy via ceRNA mechanism in some other cancers, such as in gastric cancer via miR-195/CREB1 axis and in gastric adenocarcinoma via miR-503/SHOX2 axis." (PMID 34516353, 2021). "In addition, in patients with Helicobacter pylori-infected gastric cancer, SHOX2 was among the most elevated genes after STAT3 activation, which demonstrated that SHOX2 was involved in the beginning and development of gastric carcinogenesis." (PMID 37170390, 2023).
lung adenocarcinoma (6 papers, 2021 to 2026). A carcinoma that arises from the lung and is characterized by the presence of malignant glandular epithelial cells. "A prior investigation demonstrated that the diagnostic sensitivity of SHOX2 and RASSF1A combined methylation in lung adenocarcinoma was 52.5%, whereas cytology exhibited a sensitivity of 13.3%." (PMID 38840077, 2024). "Research has demonstrated a positive association between the combined methylation levels of SHOX2 and RASSF1A and the expression of Ki-67 in early-stage lung adenocarcinoma." (PMID 38840077, 2024). "In lung adenocarcinoma, the methylation positive rates of SHOX2, RASSF1A, and TM were 91.9% (34/37), 59.5% (22/37), and 97.3% (36/37), respectively." (PMID 36691467, 2023). "Additionally, the study aims to investigate the potential of SHOX2 and RASSF1A methylation as a supplementary diagnostic tool for early lung adenocarcinoma cases with uncertain pathological diagnoses." (PMID 38840077, 2024). "We aimed to explore the role of SHOX2 in lung adenocarcinoma (LUAD)." (PMID 34262939, 2021). "In this study, SHOX2 and RASSF1A gene methylation were utilized to diagnose early lung adenocarcinoma, while surgical tissue samples were employed to mitigate the potential impact of sampling variability." (PMID 38840077, 2024). "The specificities of SHOX2, RASSF1A and LungMe® methylation in diagnosing lung adenocarcinoma from benign lesions were 97.1% (33/34), 97.1% (33/34) and 94.1% (32/34)." (PMID 38840077, 2024). "The objective of this research is to examine the involvement of SHOX2 and RASSF1A methylation in the early detection of lung adenocarcinoma, specifically in distinguishing between AIS, MIA and IA." (PMID 38840077, 2024). "In lung adenocarcinoma-derived MPE, the methylation positive rates were 91.9% for SHOX2 and 59.5% for RASSF1A, which were different from those in a previous study using histology specimens, 54.9% for SHOX2 and 46.3% for RASSF1A in adenocarcinoma." (PMID 36691467, 2023). "Methylation of the promoters of SHOX2 and RASSF1A are potentially informative biomarkers for the diagnosis of early lung adenocarcinoma (LUAD)." (PMID 35837113, 2022).
lung squamous cell carcinoma (6 papers, 2010 to 2025). "Nevertheless, the significance of SHOX2 in patients with lung squamous cell carcinoma and the underlying molecular mechanisms remain unclear." (PMID 40515636, 2025). "This phenomenon has already been evidenced for SHOX2 in squamous cell lung cancer." (PMID 27660666, 2016). "In three lung squamous cell carcinoma-derived MPE patients, both SHOX2 and RASSF1A methylation detections were positive." (PMID 36691467, 2023).
squamous cell carcinoma (6 papers, 2010 to 2024). A carcinoma arising from squamous epithelial cells. "The performance of the SHOX2 biomarker was further investigated with respect to the histological subtype (adenocarcinoma, squamous cell carcinoma, other) and the stage (I-IV, UICC)." (PMID 21047392, 2010). "And studies have shown that SHOX2/RASSF1A methylation exhibits higher sensitivity to small cell lung cancer (SCLC) and squamous cell carcinoma (SCC) than adenocarcinoma." (PMID 38996143, 2024). "Moreover, when squamous cell carcinoma (SCC) was compared to adenocarcinoma (AC), the SHOX2 gene had a significantly higher methylation rate in SCC than in AC (P < 0.001)." (PMID 28977861, 2017).
non-small cell lung carcinoma (5 papers, 2016 to 2023). A group of at least three distinct histological types of lung cancer, including non-small cell squamous cell carcinoma, adenocarcinoma, and large cell carcinoma. "For non-small cell lung cancer patients, SHOX2 promoter DNA methylation has been discovered as a diagnostic and prognostic biomarker." (PMID 37091145, 2023). "A meta-analysis showed that SHOX2 methylation had higher sensitivity (70%) and specificity (96%) than carcinoembryonic antigen and cytokeratin 19 fragment antigen 21–1 in MPE associated with non-small cell lung cancer." (PMID 37158875, 2023).
prostate carcinoma (5 papers, 2014 to 2025). A carcinoma that arises from epithelial cells of the prostate gland. "We identified a significant hypermethylation of both SEPT9 and SHOX2 in primary prostate cancer compared to NAT with an excellent diagnostic accuracy." (PMID 36139516, 2022). "The present proof-of-concept study aimed to investigate the potential and dynamics of quantitative SEPT9 and SHOX2 methylation in prostate cancer (PCa) patient tissue and ccfDNA during prostate biopsy as a diagnostic tool." (PMID 36139516, 2022).